ICAM2 (intercellular adhesion molecule 2)
Description:
Cell adhesion molecule that functions as a receptor ligand of the signaling receptor ITGAL:ITGB2/LFA-1 (lymphocyte-function associated (LFA) molecule 1) ensuring leukocyte cell-cell adhesion on resting cells. Also endothelial blood vessels receptor ligand of dendritic cell (DC) CD209 signaling receptor that mediates triggering transendothelial migration of DC presursors from blood into peripheral tissues and, subsequently, into lymphoid tissues. Mediates adhesive interactions important for antigen presentation, lymphocyte recirculation, and other cellular interactions important for immune response and surveillance (Probable).
Synonyms: CD102
Tractability: Antibody: its Gene Ontology location is reachable by antibodies, with high confidence; UniProt predicts a signal peptide or a membrane-spanning region; the Human Protein Atlas places it where antibodies can reach. PROTAC: ubiquitination databases record sites on it; its protein half-life has been measured.
Gene: Protein-coding gene on chromosome 17 (64,002,594 to 64,020,635, reverse strand). Ensembl gene ENSG00000108622.
Subcellular location: Cell membrane; Cell projection, microvillus
Subcellular location (Human Protein Atlas): Plasma membrane; Cytosol
Pathways (Reactome):
Immune System: CD209 (DC-SIGN) signaling; Immunoregulatory interactions between a Lymphoid and a non-Lymphoid cell
Extracellular matrix organization: Integrin cell surface interactions
Gene Ontology:
Molecular function: integrin binding; receptor ligand activity
Biological process: cell adhesion mediated by integrin; dendritic cell migration; leukocyte cell-cell adhesion; cell adhesion; cell-cell adhesion; signal transduction
Cellular component: cleavage furrow; membrane; plasma membrane; microvillus; cell periphery; uropod
Genetic constraint (gnomAD): Loss-of-function variants: 17 observed, 21.87 expected, observed/expected ratio (o/e) 0.78, 90% interval 0.53 to 1.17. The upper end of that interval is the gene's LOEUF score, 1.17, which puts it in group 5 of 6, group 1 being the genes least tolerant of losing a copy. Missense variants: 311 observed, 372.23 expected, observed/expected ratio (o/e) 0.84, 90% interval 0.76 to 0.92. Synonymous variants: 153 observed, 161 expected, observed/expected ratio (o/e) 0.95, 90% interval 0.83 to 1.09.
Homologues: Orthologues: chimpanzee ICAM2 (98% identical), macaque ICAM2 (85% identical), rabbit ICAM2 (68% identical), guinea pig ICAM2 (61% identical), mouse Icam2 (60% identical), rat Icam2 (56% identical), pig ICAM2 (56% identical), dog ICAM2 (53% identical). Paralogues in human: ICAM5 (31% identical), ICAM3 (30% identical), ICAM1 (29% identical), ICAM4 (22% identical).
Diseases named in the same sentence as ICAM2 in open-access papers:
ICAM2 is named in the same sentence as 71 diseases in open-access papers, as found by Europe PMC text mining. Sharing a sentence is not in itself a finding about the gene and the disease. The quoted sentences say what the papers report.
neuroblastoma (8 papers, 2008 to 2025). Neuroblastoma (NB) is the most common solid, extracranial childhood tumor. "In contrast to its role in promoting angiogenesis, ICAM-2 expression in neuroblastoma has been linked to a reduced metastatic potential." (PMID 39911389, 2025). "Consistent with the preclinical data from neuroblastoma cell lines, ICAM-2 expression was associated with favorable histologic features (exact 95% confidence interval, 62.6% to 95.3%) such as ganglionic differentiation or low-risk stage." (PMID 18978946, 2008). "Nevertheless, the data indicate that ICAM-2, α-actinin, and actin associate with each other in neuroblastoma cell lysates." (PMID 18978946, 2008). "These co-immunoprecipitation data showed that ICAM-2 associated with α-actinin and actin in neuroblastoma cell lysates." (PMID 18978946, 2008). "Consistent with our hypothesis, we observed the highest levels of ICAM-2 expression in neuroblastoma tumor cells associated with the most favorable predicted clinical outcome." (PMID 18978946, 2008). "The data herein suggest that in neuroblastoma cells the association of ICAM-2 with α-actinin and actin may represent such an interaction." (PMID 18978946, 2008). "The observed ICAM-2/α-actinin/actin association in cell lysates suggested that ICAM-2 expression in neuroblastoma cells might affect the function of the actin cytoskeleton." (PMID 18978946, 2008). "The novel findings of this study are that neuroblastoma cells express ICAM-2 and that this expression is associated with juxtamembrane distribution of actin fibers, decreased cell motility in vitro, and suppressed development of disseminated tumors in a preclinical model of metastatic neuroblastoma." (PMID 18978946, 2008). "Using these transfectants, we conducted co-immunoprecipitation assays to determine whether α-actinin or ezrin associated with ICAM-2 and/or actin in transfected neuroblastoma cells." (PMID 18978946, 2008). "While both studies show ICAM-2’s involvement in regulation of cellular adhesion and actin dynamics, they highlight its context-dependent functions—supporting tumor suppression in neuroblastoma while aiding endothelial migration and survival in angiogenesis." (PMID 39911389, 2025). "A study using neuroblastoma cells from mouse models demonstrated that ICAM-2 interacted with α-actinin, which strengthened the membrane-cytoskeleton link." (PMID 39911389, 2025). "They found striking results, showing that ICAM-2 was able to reverse the metastatic phenotype in neuroblastoma cells." (PMID 35574403, 2022). "Our data show that ICAM-2 inhibits tumor cell motility and suppresses the metastatic potential of neuroblastoma cells." (PMID 26697524, 2015). "Our lab demonstrated that ICAM-2 inhibited the development of disseminated neuroblastoma tumors in a preclinical model of metastatic neuroblastoma." (PMID 26697524, 2015). "We showed that ICAM-2 suppressed neuroblastoma cell motility and growth in soft agar, and induced a juxtamembrane distribution of F-actin in vitro." (PMID 23714211, 2013). "The goal of the study presented here was to determine if the glycosylation status of ICAM-2 influenced its function in neuroblastoma cells." (PMID 23714211, 2013). "Consistent with results obtained using neuroblastoma cells lines, ICAM-2 expression (Expression Score = 0) and metastatic potential are inversely related." (PMID 18978946, 2008). "The three lower right-hand panels demonstrate ICAM-2 staining in representative stage 4, stage 2, and stage 4S neuroblastoma tumors." (PMID 18978946, 2008). "Firstly, ICAM-2 was expressed predominantly by primary neuroblastoma cells with some degree of ganglionic differentiation, and therefore predicted low metastatic potential." (PMID 18978946, 2008). "Our long-range goal is to determine the specific protein domains essential to this regulation and to investigate the possibility that small molecule agonists can be developed to mimic the effects of ICAM-2 expression in neuroblastoma cells." (PMID 18978946, 2008).
neuroblastoma (continued). "This interaction reduced cellular invasiveness and motility, thereby supporting a more favorable clinical outcome, suggesting that ICAM-2 might act as a tumor suppressor in neuroblastoma by limiting metastasis." (PMID 39911389, 2025). "Given that the effects of ICAM2 on neuroblastoma cell phenotype are influenced by ICAM2 interaction with the cytoskeletal linker protein, we speculated that ICAM2 may interact directly with potential proteins to regulate the function of GC cells." (PMID 37759298, 2023). "Furthermore, in vitroand mouse experiments indicate that ICAM2 downregulates the metastatic potential of neuroblastoma cells by interaction with the cytoskeleton proteins, such as α-actinin and actin." (PMID 27556181, 2016). "ICAM2 downregulation has been shown in progression and metastasis of human neuroblastomas." (PMID 27556181, 2016). "Importantly, immunohistochemical analyses of primary neuroblastoma tumor specimens demonstrated that neuroblastoma cells expressing ICAM-2 are phenotypically and histologically those recognized clinically to have limited metastatic potential." (PMID 26697524, 2015). "In neuroblastoma cells, we detected an association of ICAM-2 with α-actinin, and data with competitive peptides and truncated proteins suggest that this association plays a role in the regulation of the observed ICAM-2-mediated phenotype." (PMID 18978946, 2008). "The data are consistent with the hypothesis that ICAM-2 limits the invasive potential of neuroblastoma cells." (PMID 18978946, 2008). "Therefore, we postulated that membrane-bound ICAM-2 binds to cytoplasmic ezrin or α-actinin which, in turn, binds to actin to regulate the motility—and hence the metastatic potential—of neuroblastoma cells." (PMID 18978946, 2008). "ICAM-2 protein had the expected apparent mass of 55–60 kDa in all six neuroblastoma cell lines (as well as other types of solid tumor cell lines [data not shown]), and the level of ICAM-2 expression varied with SJNB-1A>NB-1691, SK-N-SH and NB-1643>SK-N-AS and IMR-32." (PMID 18978946, 2008). "We used co-immunoprecipitation and competitive peptide assays to show that intercellular adhesion molecule-2 (ICAM-2)/α-actinin/actin may comprise such a linkage in neuroblastoma cells." (PMID 18978946, 2008). "This hypothesis was investigated by immunostaining for ICAM-2 of a neuroblastoma tissue microarray (TMA) obtained from the Children's Oncology Group." (PMID 18978946, 2008). "Also in contrast to published studies with osteosarcoma and breast cancer cells, we detected no involvement of the linker protein ezrin in the phenotype that ICAM-2 conferred on neuroblastoma cells." (PMID 18978946, 2008). "We first demonstrated using immunoblotting, that 6 of 6 neuroblastoma cells express ICAM-2." (PMID 18978946, 2008). "In tumor cells, we recently identified a unique role for ICAM-2 when we demonstrated that ICAM-2 suppressed the metastatic phenotype neuroblastoma (NB) cells." (PMID 23714211, 2013). "Since cell motility and the consequent migratory and invasive potential are essential to the metastatic process, we used a preclinical model of metastatic neuroblastoma to investigate whether ICAM-2 expression affected the development of disseminated tumors in SCID mice." (PMID 18978946, 2008). "In summary, the observed ICAM-2/α-actinin/actin interaction appears to represent a complete membrane-to-actin linkage that contributes to regulation of the motility (possibly, the invasive potential) and therefore the metastatic phenotype of neuroblastoma cells." (PMID 18978946, 2008). "Preclinical and TMA data support the hypothesis that ICAM-2 is associated with a nonmetastatic phenotype in primary neuroblastoma cells or cell lines." (PMID 18978946, 2008). "One study found that the cytoplasmic domain of ICAM2 interacts with the cytoskeletal linker protein α-actinin; this interaction promotes the non-metastatic phenotype of ICAM2 in neuroblastoma cells." (PMID 37759298, 2023).
neuroblastoma (continued). "ICAM2 serves as a tumorigenesis suppressor or promoter and interacts with α-actinin, thereby contributing to an ICAM2-mediated nonmetastatic phenotype in neuroblastoma cells." (PMID 37620448, 2023). "Throughout this review, the involvement and effect of these cell adhesion molecules, along with activated leukocyte cell adhesion molecule (ALCAM) and intercellular adhesion molecule 2 (ICAM-2) and potential for therapeutic targets in neuroblastoma is discussed." (PMID 35574403, 2022). "In neuroblastoma cells ICAM-2 inhibits cell motility independent of immune response, as we observed this inhibition in wound healing and modified Boyden chamber assays in vitro, assays that clearly lack an immune component." (PMID 26697524, 2015). "Neither the expression nor the function of ICAM-2 in neuroblastoma cells has been investigated previously." (PMID 18978946, 2008). "In neuroblastoma cell lines, ICAM-2 expression did not affect AKT activation, tumorigenic potential or chemosensitivity, as has been reported for some types of transfected cells." (PMID 18978946, 2008). "The immature neuroblastoma cells are negative for ICAM-2, but all tumor cells exhibiting histologic features of ganglionic differentiation express high levels (3+) of ICAM-2." (PMID 18978946, 2008). "Similar results were also observed with NB-1691 neuroblastoma cells transfected with pIRESneo or pIRES.ICAM2 (data not shown)." (PMID 18978946, 2008). "Ectopic expression of ICAM-2 did not affect the tumorigenic potential of neuroblastoma cells." (PMID 26697524, 2015). "These functions for ICAM-2 were independent of immune stimulation, since the tumorigenic potential of ICAM-2-expressing neuroblastoma cells as xenografts in SCID mice was unaffected and cell phenotype was altered in vitro as well as in vivo." (PMID 18978946, 2008).
atherosclerosis (7 papers, 2014 to 2026). A disease characterized by the build-up of fatty material and calcium deposition in the arterial wall resulting in partial or complete occlusion of the arterial lumen. "In this study, hypoglycemia did not result in changes in VEGFA, ICAM1, ICAM2 and VCAM1 as known mediators of endothelial dysfunction associated with atherosclerosis, stroke and myocardial infarction, as well as T2D microvascular complications." (PMID 41596469, 2026).
gastric cancer (5 papers, 2008 to 2024). A primary or metastatic malignant neoplasm involving the stomach. "In gastric cancer tissues, the decreasing expression of intercellular adhesion molecule 2 (ICAM2) was found to correlate with advanced stages and metastasis in cancer patients positively." (PMID 39457653, 2024). "In a preclinical study, adenovirus-mediated transfer of the ICAM2 gene prolonged the survival of mice with peritoneal metastases of gastric cancer." (PMID 27556181, 2016). "For example, gastric carcinoma tumor cells transfected to express ICAM-2 induce an immune response sufficient to produce a significant anti-tumor effect in immune competent mice." (PMID 18978946, 2008). "In gastric cancer cells, ICAM2 decreased the expression of radixin." (PMID 39457653, 2024). "So far, the function of ICAM2 in gastric cancer (GC) development and its associated pathomechanism is not well understood." (PMID 37759298, 2023). "Intercellular adhesion molecule 2 (ICAM2), a transmembrane glycoprotein, can promote the NEDD4L-mediated ubiquitination and degradation of RDX, thereby inhibiting the tumorigenicity and metastasis of gastric cancer." (PMID 38027016, 2023).
breast carcinoma (4 papers, 2008 to 2023). "To assess whether ICAM2 promotes LM in normal background mice model, we constructed the ICAM2-overexpressing 4T1 cells, a breast cancer cell line derived from the mammary gland tissue of a mouse BALB/c strain, for further investigation." (PMID 37620448, 2023).
pancreatic cancer (4 papers, 2014 to 2025). "The transfection of resistant cells with ICAM-1 or ICAM-2 subsequently restored the sensitivity of pancreatic tumor cells to γδ-T-cells." (PMID 40071851, 2025). "Secretion of CXCL17 and ICAM2 was significantly decreased when IPMA progressed to pancreatic cancer, contributing to immune tolerance." (PMID 40427186, 2025). "For instance, some key biomarkers have been exposed in pancreatic carcinoma, namely intercellular adhesion molecule 2 (ICAM2), anoctamin 9 (ANO9), proline-rich tyrosine kinase 2 (PYK2) and cyclin-dependent kinase 9 (CDK9)." (PMID 31412643, 2019). "In pancreatic cancer, ICAM2 has been reported to have tumor suppressor function through immune surveillance." (PMID 25146004, 2014). "Before pancreatic cancer development, particularly at the (IPMN) (intraductal papillary mucinous neoplasm) stage, increased secretion of CXCL17 and ICAM2 (intercellular adhesion molecule 2) led to the infiltration of cDCs, followed by T-cell-mediated cytolysis of tumor cells." (PMID 40427186, 2025).
Stroke (4 papers, 2022 to 2026). Sudden impairment of blood flow to a part of the brain due to occlusion or rupture of an artery to the brain. "Similar analysis of genes in the Disease and Function categories indicated that female MMP-3 KO stroke brains had decreased expression of leukocyte migration genes Ccr1, Pecam1, Mmp9, Ccl6, Icam2, and Ccl11." (PMID 39000490, 2024). "Female MMP-3 KO stroke brains also had decreased expression of blood cell adhesion genes Pecam1 and Icam2, and decreased expression of inflammatory response genes Ccr1, Cxcl1, Mmp9, Il4ra, Il6, and Il1rn." (PMID 39000490, 2024). "The volcano plot indicates significant downregulation of genes already implicated in inflammation and apoptotic cell death following stroke such as Ccr5, Casp8, Icam2, Mmp9, Pecam1, and Il6." (PMID 39000490, 2024). "Similarly, genes involved in integrin cell surface interactions including Itga10, Itgb3, Vcam1, Itgb1, Itgae, Itgb7, Itga1, Itga5, Icam1, Itgb2, Pecam1, and Icam2 were depleted in male MMP-3 KO stroke brains." (PMID 39000490, 2024). "In a proteomics stroke study, researchers identified ICAM-2, STXBP5, PLGLA, C3, and IGHV3-64 as candidate biomarkers in blood, yielding a high (75% to 88%) sensitivity for identifying stroke patients." (PMID 40362186, 2025). "Clustering analysis of DEGs in male and female stroke brains revealed that MMP-3 KO decreased expression of genes that belong to the adhesion and leukocyte extravasation pathway such as Esam, Icam1, Icam2, Mcam1, and Pecam1." (PMID 39000490, 2024). "Among them, VIM was positively correlated with the occurrence of stroke, while CARD11, ICAM2, CD19, and CCR7 were negatively correlated with the occurrence of stroke." (PMID 35722467, 2022).
melanoma (3 papers, 2011 to 2024). A malignant, usually aggressive tumor composed of atypical, neoplastic melanocytes. "Our single-cell RNA-seq data showed that zebularine treatment of melanoma cells significantly upregulated a panel of MHC-AgPPM genes, innate immune-associated genes (IFN-stimulated genes, chemokines, etc.), and genes involved in lymphocyte adhesion (such as Vcam1, Icam1, Icam2, and Sele)." (PMID 38755254, 2024). "Melanoma cell adhesion molecule/CD146, Platelet Endothelial Cell Adhesion Molecule-1/CD31, ICAM-1, and ICAM-2 are adhesion proteins participating in the recruitment of leukocytes to sites of tissue injury and inflammation." (PMID 21245959, 2011).
COVID-19 (2 papers, 2024 to 2025). A disease caused by infection with severe acute respiratory syndrome coronavirus 2. "Partly consistent with a previous MR study showing sICAM-2 lowers the risk of severe COVID-19 and in line with another MR study showing ICAM5 lowers the risk of severe COVID-19, we found ICAM-2 and ICAM-5 lower the risk of COVID-19 hospitalization." (PMID 38575325, 2024).
Crohn disease (2 papers, 2014 to 2024). A gastrointestinal disorder characterized by chronic inflammation involving all layers of the intestinal wall, noncaseating granulomas affecting the intestinal wall and regional lymph nodes, and transmural fibrosis. "ICAM-1 levels are increased in colon tissue from ulcerative colitis and Crohn’s disease, whereas ICAM-3 is elevated only in Crohn’s disease; in contrast, ICAM-2 levels are unaltered in both diseases." (PMID 38391953, 2024).
metastatic disease (2 papers, 2008 to 2015). "Results with primary tumor specimens also reflected the inverse relationship between ICAM-2 expression and predicted low-risk for progressive metastatic disease, as was seen with the preclinical model." (PMID 18978946, 2008). "The immature neuroblasts (100%) of this stage 4S tumor exhibit strong (3+) ICAM-2 expression (Expression Score = 100%×3+ = 300), again reflecting a correlation between relatively high level of expression of ICAM-2 and low potential for progressive metastatic disease." (PMID 18978946, 2008).